TGM2 (transglutaminase 2)
Description:
Calcium-dependent acyltransferase that catalyzes the formation of covalent bonds between peptide-bound glutamine and various primary amines, such as gamma-amino group of peptide-bound lysine, or mono- and polyamines, thereby producing cross-linked or aminated proteins, respectively. Involved in many biological processes, such as bone development, angiogenesis, wound healing, cellular differentiation, chromatin modification and apoptosis. Acts as a protein-glutamine gamma-glutamyltransferase by mediating the cross-linking of proteins, such as ACO2, HSPB6, FN1, HMGB1, RAP1GDS1, SLC25A4/ANT1, SPP1 and WDR54. Under physiological conditions, the protein cross-linking activity is inhibited by GTP; inhibition is relieved by Ca(2+) in response to various stresses. When secreted, catalyzes cross-linking of proteins of the extracellular matrix, such as FN1 and SPP1 resulting in the formation of scaffolds. Plays a key role during apoptosis, both by (1) promoting the cross-linking of cytoskeletal proteins resulting in condensation of the cytoplasm, and by (2) mediating cross-linking proteins of the extracellular matrix, resulting in the irreversible formation of scaffolds that stabilize the integrity of the dying cells before their clearance by phagocytosis, thereby preventing the leakage of harmful intracellular components. In addition to protein cross-linking, can use different monoamine substrates to catalyze a vast array of protein post-translational modifications: mediates aminylation of serotonin, dopamine, noradrenaline or histamine into glutamine residues of target proteins to generate protein serotonylation, dopaminylation, noradrenalinylation or histaminylation, respectively. Mediates protein serotonylation of small GTPases during activation and aggregation of platelets, leading to constitutive activation of these GTPases (By similarity). Plays a key role in chromatin organization by mediating serotonylation and dopaminylation of histone H3. Catalyzes serotonylation of 'Gln-5' of histone H3 (H3Q5ser) during serotonergic neuron differentiation, thereby facilitating transcription. Acts as a mediator of neurotransmission-independent role of nuclear dopamine in ventral tegmental area (VTA) neurons: catalyzes dopaminylation of 'Gln-5' of histone H3 (H3Q5dop), thereby regulating relapse-related transcriptional plasticity in the reward system. Regulates vein remodeling by mediating serotonylation and subsequent inactivation of ATP2A2/SERCA2 (By similarity). Also acts as a protein deamidase by mediating the side chain deamidation of specific glutamine residues of proteins to glutamate. Catalyzes specific deamidation of protein gliadin, a component of wheat gluten in the diet. May also act as an isopeptidase cleaving the previously formed cross-links. Also able to participate in signaling pathways independently of its acyltransferase activity: acts as a signal transducer in alpha-1 adrenergic receptor-mediated stimulation of phospholipase C-delta (PLCD) activity and is required for coupling alpha-1 adrenergic agonists to the stimulation of phosphoinositide lipid metabolism. [Isoform 2]: Has cytotoxic activity: is able to induce apoptosis independently of its acyltransferase activity.
Synonyms: G(h); tTG; TG(C); TGC; TG2; hTG2
Tractability: Small molecule: a structure with a bound ligand is known; a high-quality ligand is known; it has a high-quality binding pocket; it belongs to a druggable protein family. Antibody: UniProt places it where antibodies can reach, with high confidence; its Gene Ontology location is reachable by antibodies, with high confidence; the Human Protein Atlas places it where antibodies can reach. PROTAC: ubiquitination databases record sites on it; its protein half-life has been measured; a small molecule that binds it is known.
Target class: Protein-glutamine glutamyl-transferase; Enzyme; Aminoacyltransferase
Gene: Protein-coding gene on chromosome 20 (38,127,385 to 38,168,463, reverse strand). Ensembl gene ENSG00000198959.
Subcellular location: Cytoplasm, cytosol; Nucleus; Chromosome; Secreted, extracellular space, extracellular matrix; Cell membrane; Mitochondrion; Cytoplasm, perinuclear region (Isoform 2)
Subcellular location (Human Protein Atlas): Cytosol; Plasma membrane; Predicted to be secreted
Gene Ontology:
Molecular function: calcium ion binding; GTP binding; histone dopaminyltransferase activity; histone serotonyltransferase activity; peptide dopaminyltransferase activity; peptide histaminyltransferase activity; peptide serotonyltransferase activity; protein binding; protein-glutamine gamma-glutamyltransferase activity; protein-glutamine glutaminase activity; GTPase activator activity; peptide noradrenalinyltransferase activity
Biological process: apoptotic cell clearance; cellular response to cocaine; cellular response to dopamine; cellular response to serotonin; extracellular matrix organization; negative regulation of endoplasmic reticulum calcium ion concentration; phospholipase C-activating G protein-coupled receptor signaling pathway; positive regulation of apoptotic process; positive regulation of mitochondrial calcium ion concentration; positive regulation of neurogenesis; positive regulation of sprouting angiogenesis; regulation of apoptotic cell clearance; regulation of apoptotic process; bone development; peptide cross-linking; positive regulation of cell adhesion; positive regulation of small GTPase mediated signal transduction; chromatin remodeling
Cellular component: chromatin; chromosome; cytosol; extracellular exosome; extracellular matrix; focal adhesion; mitochondrion; nucleus; plasma membrane; endoplasmic reticulum; perinuclear region of cytoplasm
Genetic constraint (gnomAD): Loss-of-function variants: 54 observed, 75.07 expected, observed/expected ratio (o/e) 0.72, 90% interval 0.58 to 0.9. The upper end of that interval is the gene's LOEUF score, 0.9, which puts it in group 3 of 6, group 1 being the genes least tolerant of losing a copy. Missense variants: 842 observed, 943.53 expected, observed/expected ratio (o/e) 0.89, 90% interval 0.84 to 0.94. Synonymous variants: 374 observed, 388.88 expected, observed/expected ratio (o/e) 0.96, 90% interval 0.88 to 1.05.
Homologues: Orthologues: chimpanzee TGM2 (99% identical), macaque TGM2 (99% identical), pig TGM2 (89% identical), dog TGM2 (85% identical), mouse Tgm2 (84% identical), guinea pig TGM2 (83% identical), rabbit TGM2 (81% identical), tropical clawed frog tgm2 (61% identical), zebrafish tgm2b (53% identical), zebrafish tgm2a (48% identical). Paralogues in human: TGM6 (42% identical), TGM5 (41% identical), TGM7 (41% identical), TGM3 (38% identical), F13A1 (37% identical), TGM1 (36% identical), EPB42 (33% identical), TGM4 (32% identical).
Diseases named in the same sentence as TGM2 in open-access papers:
TGM2 is named in the same sentence as 431 diseases in open-access papers, as found by Europe PMC text mining. Sharing a sentence is not in itself a finding about the gene and the disease. The quoted sentences say what the papers report.
celiac disease (474 papers, 2005 to 2026). An autoimmune genetic disorder with an unknown pattern of inheritance that primarily affects the digestive tract. "Celiac disease autoimmunity was defined as a positive anti–transglutaminase 2 enzyme-linked immunosorbent assay test result according to the thresholds of the commercial kits used." (PMID 40184064, 2025). "IgA autoantibodies against transglutaminase 2 (TG2) are a hallmark for celiac disease and patients display a massive influx of LP PC cells." (PMID 39147924, 2024). "We have found that oxylipins are associated with risk of the autoimmune disease T1D, and TGM2 encodes for the protein transglutaminase 2, a target of autoantibodies in another autoimmune condition, celiac disease." (PMID 37057071, 2023). "Celiac disease (CeD) is defined by chronic, gluten-dependent small bowel enteropathy associated with autoantibody directed against transglutaminase 2 (TG2) and an acquired CD4+ T cell-driven immune response directed against dietary gluten." (PMID 38275990, 2023). "The adaptive immune response associated with celiac disease is largely based on the interaction between gliadin peptides and an endogenous enzyme called transglutaminase 2 (TG2)." (PMID 33435615, 2021). "A hallmark of the gluten-driven enteropathy celiac disease is autoantibody production towards the enzyme transglutaminase 2 (TG2) that catalyzes the formation of covalent protein-protein cross-links." (PMID 26244572, 2015). "Tgm2 has been implicated in inflammatory processes, such as Celiac disease, infections, cancer, neurodegenerative diseases, such as Huntington's disease and was recently found to be a key regulator of cross-talk between autophagy and apoptosis." (PMID 23226835, 2012). "Compared with controls, immunoglobulin heavy variable 5–51 (IGHV5-51) (p = 1.05 × 10−14) and tissue transglutaminase (TGM2) (p = 5.29 × 10−10), encoding for TG2, the main autoantigen in celiac disease, were two of the top up-regulated genes in intestinal biopsies from celiac cases." (PMID 40883722, 2025). "Moreover, TGM2 encodes transglutaminase 2, an enzyme involved in protein crosslinking, apoptosis, and the pathogenesis of celiac disease." (PMID 39596622, 2024). "Transglutaminase 2 (TG2), formerly known as tissue transglutaminase, expressed in apoptotic and injured cells in the gut has been implicated as the host enzyme responsible for facilitating gluten immunotoxicity in celiac disease." (PMID 38275990, 2023). "Celiac disease or gluten-dependent enteropathy is a chronic autoimmune pathology triggered by dietary gluten in genetic predisposed individuals, mediated by transglutaminase 2 IgA autoantibodies and associated with a deteriorating immune and inflammatory response." (PMID 35186332, 2022). "Antibodies to the autoantigen transglutaminase 2 (TG2) are a hallmark of celiac disease." (PMID 26160175, 2015). "Since coeliac disease (CD) is a common cause of poor growth, we previously analysed our cohort of CP patients for IgA and IgG-antibodies against gliadin and transglutaminase 2 (TG2) and found a high prevalence of seropositive patients." (PMID 24804082, 2014). "They identified a specific protein signature for celiac disease involving 20 proteins, three being the transglutaminase 2, ITGB7, and CPA2." (PMID 41158112, 2026). "Transglutaminase 2 (TG2) plays an essential role in the pathogenesis of celiac disease (CD) by modifying gliadin peptides." (PMID 40787731, 2025). "Transglutaminase 2 (TG2)-mediated enzymatic modification of gliadin peptides plays a major role in the pathogenesis of celiac disease (CD)." (PMID 41048571, 2025). "In celiac disease (CeD), a gluten-dependent autoimmune disorder, transglutaminase 2 (TG2), deamidates selected glutamine residues in gluten peptides, while HLA-DQ2 presents deamidated antigens to inflammatory T cells." (PMID 40875488, 2025).
celiac disease (continued). "The search string was (“Transglutaminase 2 Inhibitor” OR “Regulatory T Cells”) AND (“Celiac Disease” OR “Coeliac Disease” OR “Gluten-sensitive enteropathy”) AND (“Intestinal Damage” OR “Immune Tolerance” OR “Adverse reaction” OR “quality of life”)." (PMID 40575215, 2025). "Celiac disease was determined based on transglutaminase 2 (TG2), immunoglobulin A (IgA), and G (IgG) in serum samples." (PMID 39257416, 2024). "Celiac disease is characterized by villous atrophy and the presence of autoantibodies targeting transglutaminase 2 (TG2), an enzyme that deamidates gluten." (PMID 38701071, 2024). "Benchmarking potential biological targets, including transglutaminase-2 inhibitors, for the treatment of celiac disease." (PMID 38550585, 2024). "This is analogous to transglutaminase 2 (tissue transglutaminase), the autoantigen in coeliac disease and transglutaminase 3 (epidermal transglutaminase), the autoantigen in dermatitis herpetiformis, the skin manifestation of gluten sensitivity." (PMID 38674899, 2024). "Transglutaminase 2 (TG2) plays a pivotal role in the pathogenesis of celiac disease (CeD) by deamidating dietary gluten peptides, which facilitates antigenic presentation and a strong anti-gluten T cell response." (PMID 38914866, 2024). "Diagnosis of celiac disease in adults is based on positive serology of anti-transglutaminase 2 (anti-TG2) antibodies, which are produced as a response to gluten ingestion and histological confirmation of intestinal villous atrophy." (PMID 39257416, 2024). "In both IgAN and celiac disease, the transferrin receptor (TFR) is associated with transglutaminase 2 (TG2), both of which are present in enterocytes and mesangial cells." (PMID 38720942, 2024). "Enzymatic modification of gliadin peptides by human transglutaminase 2 (TG2) is a key mechanism in the pathogenesis of celiac disease (CD) and represents a potential therapeutic target." (PMID 36902226, 2023). "For example, ERW1041E is a TGM2-specific irreversible inhibitor that has been used to explore the role of TGM2 in hypoxia-induced pulmonary, celiac disease and cardiac fibrosis." (PMID 36831225, 2023). "Outside the public media’s recent fascination with glutens and celiac disease, TGM2 remains a relatively understudied enzyme, despite being one of the most ubiquitously distributed isozymes in the body." (PMID 36831672, 2023). "Formation of complexes between transglutaminase 2 (TG2) and gluten can mechanistically explain why TG2 serves both as B-cell autoantigen and as an enzyme that creates deamidated gluten epitopes in coeliac disease (CeD)." (PMID 37368893, 2023). "The enzyme transglutaminase 2 (TG2) plays a key role in celiac disease (CeD) pathogenesis, both as a CeD autoantigen and through the generation of immunogenic, deamidated gliadin peptide epitopes recognized by the T-cells." (PMID 37445994, 2023). "Enzymatic modification of gliadin peptides by human transglutaminase 2 (TG2) is a central step in celiac disease (CD) pathogenesis." (PMID 35216364, 2022). "Key immunological processes in celiac disease involve interaction between transglutaminase 2 (TG2)‐specific B cells and gluten‐specific T cells." (PMID 35715890, 2022). "There were studies showing that A2M played an important role in the function of many immune cells, and TGM2 was involved in several autoimmune diseases such as celiac disease, inflammatory bowel disease, osteoarthritis, and idiopathic inflammatory myopathies." (PMID 35406685, 2022). "First of all, celiac disease and IgAN share molecular mechanisms that involve IgA1, transglutaminase 2 (TG2), and overexpression of Transferrin Receptor (TfR1, or CD71), a non-classical IgA receptor." (PMID 36467425, 2022). "The adaptive immune response of celiac disease (CeD) involves presentation of gluten peptides to CD4+ T cells by transglutaminase 2 (TG2) specific B cells." (PMID 35715890, 2022).
celiac disease (continued). "A hallmark of celiac disease is the gluten-dependent production of antibodies specific for deamidated gluten peptides (DGP) and the enzyme transglutaminase 2 (TG2)." (PMID 34731200, 2021). "Presence of celiac disease-specific IgA-class autoantibodies, determined by endomysial (EmA) and transglutaminase 2 autoantibody (TG2-Ab) assays, supports the diagnosis and serves as a valuable tool in selecting patients for endoscopy." (PMID 31239486, 2019). "Autoantibody reactivity to transglutaminase 2 closely corresponds with the gluten intake and clinical presentation in affected patients, serving as a highly useful biomarker in the diagnosis of celiac disease." (PMID 30127251, 2018). "The frequency of IGHV genes within the IGHV5 family, which is highly used in the transglutaminase 2-specific auto-antibodies induced by gluten in celiac disease (CD), was, on the other hand, increased at the same time point." (PMID 29755475, 2018). "In celiac disease, a significantly enhanced autoantibody response to the transglutaminase 2 (TG2) enzyme, also known as tissue transglutaminase (tTG), is a hallmark of the pathogenic process and signifies a loss of tolerance to wheat gluten." (PMID 30127251, 2018). "A specific characteristic of coeliac disease is the generation of immunoglobulin class A (IgA) antibodies towards the main autoantigen, transglutaminase 2 (TG2)." (PMID 30522434, 2018). "In coeliac disease, ingestion of gluten induces the production of transglutaminase 2 (TG2)-targeted autoantibodies by TG2-specific plasma cells present at high frequency in the small intestinal mucosa in untreated disease." (PMID 30522434, 2018). "TGM2 has a pivotal role in celiac disease pathogenesis through generating immunogenic peptides from gliadin and because of the appearance of pathologic anti-TGM2 antibodies during the course of the disease." (PMID 28248968, 2017). "Initiation of celiac disease is triggered in the gastrointestinal tract by transglutaminase 2 (TG2) assisted deamidation of gluten peptides." (PMID 28250436, 2017). "Celiac disease is a prevalent enteropathy with autoimmune features including highly disease-specific autoantibodies to the enzyme transglutaminase 2 (TG2) and selective immune killing of enterocytes." (PMID 26244572, 2015). "The enzyme transglutaminase 2 (TG2) plays a crucial role in the initiation of celiac disease by catalyzing the deamidation of gluten peptides." (PMID 25816160, 2015). "In line with this idea, patients suffering from celiac disease, which typically form autoantibodies to Tgm2, are less likely to have a diagnosis of hypertension." (PMID 26063971, 2015). "TGM2 inhibitors have been reported as a treatment modality for various conditions, such as celiac sprue, Huntington's disease, and certain types of cancer." (PMID 25247996, 2014). "The humoral immune response in celiac disease also includes antibodies to deamidated sequences of gliadin and to the autoantigen transglutaminase 2 (TG2), which are highly specific and sensitive serologic markers of the condition." (PMID 23823064, 2013). "A characteristic feature of celiac disease is the presence of circulating autoantibodies targeted against transglutaminase 2 (TG2), reputed to have a function in angiogenesis." (PMID 23824706, 2013). "Tissue transglutaminase 2 (TG2) and TG3 have been implicated as the autoantigens in celiac disease and dermatitis herpetiformis respectively." (PMID 24204900, 2013). "TGM2 activity is also well known to be involved in celiac disease (CD), a chronic, auto-immune mediated, small-intestinal disorder characterized by inflammatory injury to the mucosa following ingestion of wheat gluten." (PMID 22389694, 2012). "Effect of moderate (3-5g) and low (1-3g) amounts of gluten on serum transglutaminase 2 (TG2) antibodies and small bowel mucosal TG2-targeted autoantibody deposits in treated celiac disease patients." (PMID 22115041, 2011).